IL18 (interleukin 18)
Diseases named in the same sentence as IL18 in open-access papers (continued):
Sharing a sentence is not in itself a finding about the gene and the disease.
infection (continued). "The activation of NLRP3 inflammasome by microbial stimuli plays a critical role in regulating IL-1β and IL-18 secretion during infection." (PMID 34564598, 2021). "IAV‐infected mice require ethical euthanasia on day 4 following infection and we next examined the intracellular expression of pro‐IL‐1β and pro‐IL‐18 at this timepoint." (PMID 33834544, 2021). "To further investigate the role of IL-18 in NK cell metabolism in vivo during infection and inflammation, we generated a mouse model that lacks Il18r1 specifically in NK cells." (PMID 34093543, 2021). "Subsequent to in vivo IL-18 neutralization, analysis of lung lymphocytes at day 5 post-infection revealed a significant decline in the frequency of total NK cells and IFN-γ+ NK cells by 2.2-fold for both." (PMID 34305935, 2021). "In this study we focused on the mechanisms behind inflammasome activation in MDMs and found that HIV can trigger both IL-1β and IL-18 upon infection." (PMID 33861800, 2021). "IL-18, which is an immunoregulatory cytokine, is a member of the IL-1 family and its serum levels are significantly elevated in a state of infection." (PMID 34444668, 2021). "Some of these cytokines, including IL-1β and IL-18, are secreted following activation of the inflammasome pathway during IECs’ infection." (PMID 33801524, 2021). "Cryptosporidium triggers an enterocyte intrinsic inflammasome leading to the release of IL-18 from the infected cell, and infection also results in pronounced production of interferon λ." (PMID 34866573, 2021). "Infection with P. ciferrii increased production of IL-1β, and IL-18 proteins and mRNAs in bMECs (P < 0.05), with more profound increases in bMECs infected with P. bovis (P < 0.05)." (PMID 34895324, 2021). "The levels of IL-1β and IL-18 induced by inflammasome activation were significantly higher in Mint3–/– mice on day 3 of infection." (PMID 33854054, 2021). "At 2 h postinfection, IL-1β and IL-18 production was reduced in both parental and NLRC4 KO THP-1 cells infected with the flagellin- or T3SS/flagellin-deficient strain in comparison with infection with wild-type S. Typhimurium." (PMID 33380493, 2021). "In the CSF, levels of MCP-1, IL-1Ra, IL-2, G-CSF, and IL-18 started increasing on day 5 post-infection." (PMID 34001896, 2021). "Again, the ΔNLRP3 cells did not produce IL-18 in response to HSV-1, but did produce a modest, but statistically significant, amount of IL-18 after infection with HSV-1/UV." (PMID 32101570, 2020). "In vivo, IL-18 releases in serum and parasite burdens in peritoneal exudate cells were significantly increased in PG-treated WT mice after infection with N. caninum; however, IL-18 productions and parasite burdens were not changed in PG-treated Nlrp3−/− mice." (PMID 32891167, 2020). "IL-18 has anti-infection, anti-tumour and anti-hypersensitivity effects, and is related to the development of inflammatory lesions in tissues and the presence of autoimmune diseases." (PMID 33327639, 2020). "First, an obvious increase in the levels of IFN-γ, IL-6, IL-1β, IL-1Ra, IL-18, IL-5, IL-8 was detected in the early (3 dpi) stage of infection, indicating the activation of innate immune responses, such as monocytes and NK cells." (PMID 33180882, 2020). "We subsequently analyzed the kinetics of the most intensive pro-inflammatory cytokines including TNF-α, IL-1β, IL-6, and IL-18 in sera of pigs upon SY18 infection." (PMID 33553280, 2020). "infection but also provides evidence showing that the Dectin-1 receptor facilitates IL-18 production for the host generation of candidacidal antibodies." (PMID 32765468, 2020). "The study also reported that IL-2, IL-6, IL-18, and GM-CSF were significantly higher during the acute stages of B. rossi-infection." (PMID 32133380, 2020). "IL-18 also trended with the number of SIV challenges to infection (Spearman correlation: R = 0.46, p = 0.1311)." (PMID 32163525, 2020).
infection (continued). "Inhibition of caspase‐4 by NleF blocks secretion of processed IL‐18 following infection of Caco‐2 human IEC‐like cells with EPEC at 4 days post‐infection with C. rodentium in mice, which results in reduced neutrophil recruitment." (PMID 32185892, 2020). "Although activated T-cells and natural killer cells are regarded as the major source of IFNγ during early infection, macrophages are also capable of secreting this cytokine in the presence of IL-12 and IL-18." (PMID 33352656, 2020). "It is shown that cells treated with Z. morio hemolymph produced significantly less IL-1β and IL-18 as compared to the infected-only group 18 and 24 h post-infection." (PMID 32998225, 2020). "Inflammasome-mediated secretion of IL-1β and IL-18 is aimed at eliminating the infectious pathogen through the induction of secondary mediators and the recruitment of additional immune cells to the infection site and/or pyroptosis of the infected cells." (PMID 32801995, 2020). "UV irradiating the virus prior to infection also leads to IL-18 production in unstimulated primary macrophages, but replication competent HSV-1 does not result in IL-18 release without pre-treatment with IFNγ." (PMID 32101570, 2020). "Non-cytotoxic ILC1s, which are stimulated by the presence of Il-12 and Il-18, confer immunity to infection with intracellular bacteria and protozoa, while Il-1β/Il-23-dependent ILC3s response protects the host from infection with extracellular bacteria." (PMID 33255175, 2020). "At four hours post infection, little IL-18 was detectable in supernatants from M1 macrophages, while at eight hours post infection, IL-18 was significantly higher in M1 macrophages infected with HSV-1 compared to those infected with HSV-1/UV." (PMID 32101570, 2020). "The NLRP3 inflammasome controls the maturation and secretion of the proinflammatory cytokines IL-1β and IL-18 and is important for the innate immunity against pathogen infection." (PMID 32582195, 2020). "The production of pro-inflammatory cytokines as IL-1β and IL-18 by monocytes and macrophages at this early interaction will dictate much of the infection evolution." (PMID 31961876, 2020). "RAR signaling-dependent IL-18 promotes epithelial cell shedding as well as mucosal IFNγ production to orchestrate resistance to infection." (PMID 32330185, 2020). "We quantified levels of IL-12p70, IL-18 and IL-23 in lung parenchyma at days two and seven post-infection." (PMID 32517114, 2020). "For the case of Toxoplasma, inflammasome components NLRP1 and NLRP3 respond to infection resulting in IL-1β and IL-18 release, in turn promoting resistance to infection." (PMID 33505924, 2020). "Macrophages from AIM2-deficient mice were highly susceptible to intratracheal infection with Mtb, and this deficiency resulted in severe inhibition of the AIM2 inflammasome, associated with defective IL1 and IL18 production and impaired Th1 responses." (PMID 32373118, 2020). "During in vitro infection with L.m, IL-12 and IL-18 are secreted by infected phagocytic cells, which then activate IFN-γ production by NK cells." (PMID 33082490, 2020). "IL-18 is an important regulator of the immune response and is known to be an interferon-γ inducing factor that induces cell resistance to infection." (PMID 32309219, 2020). "WT BMDMs had increased secretion of IL-18 following infection with C. albicans or A. fumigatus, whereas the Zbp1–/– and Zbp1ΔZα2/ΔZα2 BMDMs had significantly reduced IL-18 release compared with the WT." (PMID 33109609, 2020). "IL-18, together with IL-1β, serves in activation of downstream inflammation signaling in a state of infection and injury." (PMID 32297262, 2020). "Infection with B. thailandensis triggered caspase-1 mediated release of IL-1β and IL-18 and caspase-11 induced activation of the NLRP3 inflammasome leading to death of infected lung epithelial cells by pyroptosis in mice." (PMID 33329561, 2020).
infection (continued). "Together, these confirm the cerebral contribution to the elevated IL-18 level in the CSF during SE infection." (PMID 31803186, 2019). "IL-22 was instead required for the production of IL-18 late in infection, as the peak production at 14 days post-infection was abrogated in Il22−/− mice." (PMID 31681274, 2019). "In agreement with previous findings, IL-18 showed a bimodal production, with a first peak in the initial phase of infection and a second one in a later phase." (PMID 31681274, 2019). "For instance, in mice the colonization by Tritrichomonas musculis leads to inflammasome activation, promoting the release of the pro-inflammatory cytokine IL-18 and preventing infection by bacteria." (PMID 30643702, 2019). "Results showed an upregulation of proinflammatory cytokines, including interleukin-1β and interleukin-18, and macrophage infiltration in bursa in response to vvIBDV infection." (PMID 31632367, 2019). "Infection by P. yoelii 265 or P. berghei ANKA increased the production of IL-18, IL-12p40 and IFN-γ." (PMID 30717382, 2019). "Enteral feeding reduced the infection-induced IL-18 response, as shown by lowered abundance of IL-18 and IL-18 BP in CSF and plasma and decreased IL-18 transcription in brain tissues." (PMID 31803186, 2019). "The administration of anti-IL-18 neutralizing Ab to mice exacerbated infection with P. berghei ANKA, impaired host resistance, and shortened the mean survival time." (PMID 30717382, 2019). "Mechanistically, ingenuity pathway analyses revealed a tilt in the anti‐inflammatory IL‐10 versus pro‐inflammatory IL‐1β and IL‐18 balance during CHIKV nsP‐mutant infection that modified acute antiviral and cell signaling canonical pathways." (PMID 31015278, 2019). "Infection experiments with Il18−/− mice and the administration of recombinant IL-18 to caspase-1−/− mice showed that IL-18 was not important for resistance to the intestinal phase of infection, but rather to the systemic infection." (PMID 30717382, 2019). "IL-18 levels are elevated in the sera of HIV-infected patients 3-to-6 years after infection, and decrease thereafter." (PMID 30717382, 2019). "A series of studies reported the upregulation of proinflammatory cytokines, such as IL-1β, IL-6, IL-12, IL-8, and IL-18, in vvIBDV infection both in vitro and in vivo." (PMID 31632367, 2019). "As IL-22 promotes NLRC4 activity in infection, this highlights the cross-talk between IL-22 and IL-18 in VVC." (PMID 31681274, 2019). "In a mouse study, Kinoshita and colleagues showed that multiple doses of IL-18 restored a state of reduced immune function after injury suggesting the medical application of IL-18 for infections." (PMID 30717382, 2019). "In our study, both IL-1β and IL-18 significantly increased during infection with vvIBDV, which was in accordance with the inflammation detected by histopathological analysis." (PMID 31632367, 2019). "We found that the expression of eight genes, including Il18, Il36b, Il17rc, Tnfsf10, Tnfsf11, Tnfsf14, Tnfsf15, and Il1a, were closely correlated with the severity of HAdV-55 infection." (PMID 30787914, 2019). "IL-18 restored the burn-related decrease in activity of neutrophils and enhanced phagocytosis and ROS production to prevent infection by methicillin-resistant Staphylococcus aureus." (PMID 30717382, 2019). "During infection, IL-18 levels remained consistently higher in Viperin−/− mice, whereas IL-22 levels increased in WT animals during infection to reach levels comparable with Viperin−/− animals at 6 dpi." (PMID 30665948, 2019). "The transcription levels of IL-1β (at 12 and 24 h.p.i.)and IL-18 (from 12 to 36 h.p.i.)were significantly (P < 0.05) increased in the vvIBDV infection group compared with the corresponding control groups." (PMID 31632367, 2019). "Our data also demonstrate that TLR11xCasp1/11-/- mice given IL-18 during infection augments the absolute numbers of peritoneal and splenic CD8+IFN-γ+ T cells, IFN-γ+ NK cells, and IFN-γ+ neutrophils." (PMID 31194844, 2019).
infection (continued). "Such IL-33 production, particularly in the early phases of infection, can act in synergy with IL-18 and IL-1α/β in the recruitment of NK, iNKT, and T cytotoxic cells." (PMID 31507607, 2019). "Although IL-1β was clearly associated with immunopathology in VVC, our study showed that additional inflammasome-dependent cytokines, such IL-1α and IL-18, were produced during infection." (PMID 31681274, 2019). "IL-18 contributed to the development of immunopathological findings in the small intestine after the oral high-dose infection of T. gondii via the induction of IFN-γ production." (PMID 30717382, 2019). "Since IL-18 levels were unaltered during in vivo infection, we further determined if this cytokine exerts some effects during HMPV disease." (PMID 30964929, 2019). "In a herpes simplex virus (HSV-1) infection mouse model, the administration of IL-18 prior to infection markedly improved survival through T and B cell independent enhancement of IFN-γ induced NO." (PMID 30717382, 2019). "On the other hand, after 48h infection, IL18 and RFX1 appeared significantly downregulated in THP-1-derived macrophages infected with both L. (L.) infantum MHOM/TN/80/IPT1 and L. (V.) sp." (PMID 29867904, 2018). "Because macrophages and DCs are able to produce large amounts of IL-15 and IL-18, we analyzed IL-15 and IL-18 mRNA levels in splenocytes from FV-infected and Treg depleted animals during initial infection." (PMID 30210499, 2018). "And various studies show that inflammasome-mediated IL-18 or IL-1β plays important roles in controlling pathogens and promoting adaptive immune response against infection." (PMID 30105037, 2018). "In contrast, mnd2tg mice exhibited heightened serum IL-18 levels 40 hours post-infection compared to littermate controls, concomitant with larger increases in the frequency of IFNγ-producing splenic NK cells." (PMID 29855523, 2018). "The mature caspase 1 proteolytically cleaves cytosolic pro-IL-1β and pro-IL-18, which are then secreted as inflammatory cytokines, which activate the inflammatory arm of the immune response to infection." (PMID 30013955, 2018). "Infection of mice deficient in NLRP3, ASC, and caspase-1/11 resulted in decreased production of IL-18 and reduced IFN-γ in serum." (PMID 30105037, 2018). "While miR-150 targets IL-10 and IL-18 in leukocytes, microRNA-342 contributes to broad host cell immunity against infection." (PMID 30332984, 2018). "Consistent with previous reports, infection with MCMV for 40 hours induced IL-18 in the serum and led to MCMV-specific IFNγ production by splenic NK cells in wild-type controls, whereas these responses were dampened in Casp1/11−/− mice." (PMID 29855523, 2018). "In our study, we only found significant difference of TNF-α response in the 2000 CFU level of infection between the two strains, same as other cytokines including IL-4, IL-10, GM-CSF, IL-1β, IL-2, IL-6, IL-13, and IL-18." (PMID 30577452, 2018). "There have been suggestions that the extended IL-1 cytokine family (IL-1α, IL-1β, IL-18, IL-33, IL-36α, IL-36β, and IL-36γ) might also act as DAMPs and stimulate necrosis-initiated sterile inflammation, as well as amplify inflammation in response to infection-associated tissue injury." (PMID 29686666, 2018). "In vivo, we show that HtrA2 limits IL-18-dependent early inflammatory responses to MCMV (40 hours post-infection)." (PMID 29855523, 2018). "The protective immunity against the TB pathogen is said to be mediated by cytokines such as IFN-γ, TNF-α, IL-12, IL-6 and IL-18 during the initial stage of infection." (PMID 30583589, 2018). "In contrast, serum IL-6 concentrations increased during sJIA flare-up and with the complication of infection; serum IL-18 concentrations increased before clinical disease activity." (PMID 29622022, 2018). "IL-23 promotes neutrophil recruitment early in the course of infection, while IL-18 plays a pivotal role in the perpetuation of the inflammatory response." (PMID 29394248, 2018).
infection (continued). "Active caspase-1 cleaves pro-IL-lβ and pro-IL-18 into mature IL-lβ and IL-18, which are essential for coordination of immune responses to pathogen infection through allograft neutrophil sequestration, mononuclear phagocyte recruitment, and T-cell activation." (PMID 30087667, 2018). "A virus lacking the C12L gene (vΔC12) was attenuated after intranasal infection of mice and there was increased IL-18 and enhanced NK-cell cytotoxicity early at 3 days post-infection (dpi) in the lungs." (PMID 29495547, 2018). "The mature caspase-1 then proteolytically cleaves cytosolic pro-IL-1β and pro-IL-18, which are subsequently secreted as inflammatory cytokines that activate the inflammatory arm of the immune response to infection." (PMID 30013955, 2018). "Inflammasomes can be triggered by infection or stress, and once activated, caspase-1 is responsible for processing the precursors of IL-1β and IL-18 into their mature forms, which are secreted into the extracellular environment." (PMID 29773990, 2018). "The authors suggest monitoring serum concentrations of IL-18 and IL-6 for evaluation of disease activity in sJIA and to detect the complication of infection." (PMID 29622022, 2018). "IL-18 exerts important effects on the initiation of the adaptive Th1 cellular responses to infections by inducing IFN-γ." (PMID 30105037, 2018). "We chose to measure IL-23, IL-18 and sRAGE as potential markers with biological plausibility and some evidence suggesting utility in diagnosis of infection." (PMID 29394248, 2018). "The NLRP3 inflammasome responds to infection and tissue damage, and rapidly escalates the intensity of inflammation by activating interleukin (IL)-1β, IL-18 and cell death by pyroptosis." (PMID 30069026, 2018). "We then used ELISA to measure IL-1β, IL-18 and IL-17 levels in serum and/or tissue homogenates of mice 3 days after infection with 109 STm." (PMID 29253868, 2017). "Infection of Mf4/4 macrophages with both strains led to caspase-1 activation and IL-1β and IL-18 production, as well as activation of caspases-3, -7, -8, and -9." (PMID 28280602, 2017). "NK cell proliferation as well as IL-15 and IL-18 release by macrophages and DCs occurs early during infections." (PMID 28904191, 2017). "Caspase-4 pro-enzyme and pro-IL-18 protein expression was found to be constitutive, whereas pro-IL-1β was induced by P. aeruginosa wild-type infection, reduced by infection with the ΔpopB mutant and very weakly induced by infection with the PA14 ΔflgK mutant." (PMID 28469996, 2017). "Although Il18−/− mice were shown to be resistant to T. cruzi, discrepancy between the outcomes in Il18r1−/− versus Il18−/− mice was also previously documented for infection with M. tuberculosis and in autoimmunity." (PMID 28895840, 2017). "Among the cytokines tested, the IL-18 gene had the strongest response (fold change >32) in both the bursa and spleen, indicating its importance in protection from vaccination during infection." (PMID 28837660, 2017). "During infections, IL-18 can be secreted by DCs and macrophages, which were also highly activated during high-dose FV infection." (PMID 28904191, 2017). "Our data showed that both the South American (PRVABC59) and Nigerian (IBH30656) strains of ZIKV increased transcript levels of IL-1 and IL-18 at 24 hours post infection, confirming an activation of inflammasome pathway." (PMID 29167459, 2017). "An increased production of IL-1 and IL-18 by monocytes can enhance inflammation and significantly impact the outcome of the infection." (PMID 29167459, 2017). "We have shown that IL-18 released in pathologically relevant situations, such as from epithelium after infection or from myeloid cells in lymphoid aggregates, has a spatially limited function with respect to its rapid innate regulation of IFNγ." (PMID 28830544, 2017). "The IL-18 expressions were up-regulated at 8-, 42- and 14 - folds at days 1, 3 and 4 post infection while the CXCLi2 expressions at 7-, 21- and 12- folds." (PMID 28569155, 2017).